RN7SKP20 (RN7SK pseudogene 20)
Gene: Miscellaneous RNA gene on chromosome X (13,596,236 to 13,596,548, forward strand). Ensembl gene ENSG00000199622.
Homologues: Orthologues: chimpanzee 7SK (99% identical), guinea pig 7SK (59% identical). Paralogues in human: 7SK (79% identical), RN7SKP255 (76% identical), RN7SKP79 (75% identical), RN7SKP185 (75% identical), RN7SKP62 (74% identical), RN7SKP71 (74% identical), RN7SKP174 (74% identical), RN7SKP176 (74% identical), RN7SKP203 (74% identical), RN7SKP204 (73% identical), RN7SKP217 (73% identical), RN7SKP48 (73% identical), and 284 more.